MMP13 (matrix metallopeptidase 13)
Diseases named in the same sentence as MMP13 in open-access papers (continued):
Sharing a sentence is not in itself a finding about the gene and the disease.
infection (30 papers, 2012 to 2025). The state of being infected such as from the introduction of a foreign agent such as serum, vaccine, antigenic substance or organism. "Concerning matrix proteins, the real time QPCR assay confirmed that the pronephric expression of both mmp9 and mmp13 was up-regulated 5 days post infection with F. psychrophilum in resistant as well as in susceptible fish." (PMID 22720048, 2012). "Consequently, we uncovered distinct TJ disturbances of claudins, associated with upregulation of MMP-8 and MMP-13 expression in infected CP in vivo, which was confirmed by in vitro infection of primary CP epithelial cells." (PMID 35027063, 2022). "In teleosts, MMP-13 is required for normal embryogenesis (zebrafish) and is up-regulated following infection (Japanese flounder, channel catfish, and rainbow trout)." (PMID 40006985, 2025). "The data show an elevated expression of both DCLK1-S and MMP13 in response to CR infection, followed by a moderate decrease in their expression in CR+DBZ-treated samples." (PMID 40839695, 2025). "For example, wearable biosensors functionalized with peptides can be developed to detect infection-related biomarkers like S. aureus enzymes and inflammation markers such as MMP-13." (PMID 41584510, 2025). "The levels of MMP-13 protein in the mouse gingival epithelial layer after 28 days of infection with A. actinomycetemcomitans were measured by ELISA." (PMID 26474296, 2015). "We next show that adeno-sh-SOCS3 infection of MC3T3-E1 cells resulted in a significant augmentation of MMP-13 gene expression induced by LPS stimulation when compared with cells infected with control virus (3.8 fold induction vs 53 fold induction, p < 0.001)." (PMID 23638389, 2013). "It is of note that Il6 which codes for proinflammatory cytokine IL-6, an important regulator of the acute-phase response to injury and infection, was downregulated in Mmp13−/− tissues at both 7 d and 14 d (FC∼1 and FC∼1.2, respectively)." (PMID 22880047, 2012). "The changes in the other four genes were more complex, but also depended on the time points: At day 3 post infection, Balb/c mice produced more MMP-13 and less MMP-8, MMP-9, and TIMP-1, but this trend was reversed at three later time points." (PMID 22665968, 2012). "In addition, adeno-sh-SOCS3 infection of primary calvarial osteoblasts resulted in a significant augmentation of MMP-13 gene expression induced by LPS stimulation when compared with cells infected with control virus (p < 0.05)." (PMID 23638389, 2013). "Interestingly, reduced MMP13 expression found in infected STAT3 KO mice 28 days after infection is consistent with the increased collagen I protein content in infected STAT3 KO mice 28 days after infection." (PMID 22675647, 2012). "In this study, MMP13 represented a reliable target gene to evaluate pro-inflammatory status of macrophages in horses because IFNγ and EIAV infection considerably increased its expression." (PMID 39772115, 2024). "Our results demonstrated that overexpression of activin A via recombinant activin A or Ad‐activin A infection triggered the productions of MMP3, MMP13, and COX‐2." (PMID 36950748, 2023). "Higher collagen deposition after infection in Cyb5r3 SPC–KO mice was accompanied by significantly higher transcript levels of Mmp12, Mmp13, Mmp14, and tissue inhibitor of metalloproteinases 1 (Timp1) but neither Timp2 nor Timp3." (PMID 36749633, 2023). "All three collagenases (MMP1, MMP13 and CTSK) tested demonstrated increased expression in response to infection." (PMID 34805001, 2021). "A significant increase in the expression of MMP1, MMP3, MMP9, MMP12, MMP13, and MMP14, was noted in Mtb-AG infected, compared with Mtb-SC-infected rabbit lungs, at both 1 and 4 weeks post infection." (PMID 34732811, 2021).
infection (continued). "To do this, we overexpressed Prok2 in primary-culture chondrocytes using Ad-Prok2 infection and evaluated the expression levels of key matrix-degrading enzymes, including MMP3, MMP13, and ADAMTS5, which play pivotal roles in cartilage degradation during OA pathogenesis." (PMID 38057865, 2023). "Similarly, in the testicular parenchyma from males with early infection (acute infection without tissue cysts), we observed that MMP-13 gene expression was upregulated compared to males with chronic infection." (PMID 34294155, 2021). "Furthermore, infection of F. nucleatum in human epithelial cells promotes cellular migration, possibly via stimulation of Etk/BMX, S6 kinase p70, and RhoA kinase and increases the production of MMP-13 (collagenase 3) via the activation of mitogen-activated protein kinase p38." (PMID 32867334, 2020). "In chondrocytes overexpressing ERRγ via infection with Ad-Esrrg, MMP-3 and MMP-13 mRNA levels were dramatically elevated without affecting MMP-12 and ADAMTS5." (PMID 33261216, 2020). "We found that overexpression of ERRγ via infection with Ad-Esrrg significantly elevated the mRNA levels and extracellular secreted protein levels of MMP3 and MMP13, without affecting ADAMTS4 or -5." (PMID 29247173, 2017).
inflammation (6 papers, 2006 to 2025). Aberrant reaction of the microcirculation characterized by movement of fluid and leukocytes from the blood into extravascular tissues. "MMP9 and MMP13 expressions are also elevated in cartilage pathologies as well as in synovial inflammation and have been discussed as biomarkers for OA." (PMID 36627721, 2023). "Furthermore, synovial inflammation and cartilage degradation create a pathological feedback loop—synovial–cartilage crosstalk—whereby inflammatory cytokines upregulate MMP-13, while cartilage breakdown products amplify inflammation." (PMID 40870506, 2025). "Furthermore, inhibition of YAP1 by Vt, VPs, or MVPs significantly reduces the percentage of MMP13‐positive cells in the synovial explants, corroborating previous findings that inhibition of YAP1 can regulate synovial inflammation." (PMID 38044289, 2024). "Although the results of our work and published studies seem to argue for a MMP13-dependent contribution during the pathogenesis of chronic intestinal inflammation and intestinal fibrosis, the prognostic and/or predictive value of MMP13 levels has not been fully addressed yet." (PMID 37207229, 2023).
degenerative disease (5 papers, 2011 to 2016). "In OA, a progressive degenerative disease, proteolytic degradation of cartilage by matrix-degrading enzymes, such as MMP-13 and ADAMTS5, is a hallmark." (PMID 24007463, 2013). "TGF-β is released into the ECM upon cleavage and fragmentation of the decorin core protein, and unbound TGF-β in turn leads to increased MMP-13 expression, downstream inflammation, and accelerated degeneration of the ECM that are inextricably linked with degenerative disease." (PMID 26341258, 2015).
peripheral neuropathy (5 papers, 2020 to 2025). A disorder affecting the peripheral nervous system. "Finally, we show that MMP-13 dysregulation also underlies paclitaxel-induced peripheral neuropathy in mammals, indicating that epidermal mitochondrial H2O2 and its effectors could be targeted for therapeutic interventions." (PMID 32132628, 2020). "MMP-13, a member of the peptidase M10 family of matrix metalloproteinases (MMPs), has been reported to promote paclitaxel-induced peripheral neuropathy." (PMID 41394816, 2025). "Upregulation of MMP-13 by paclitaxel has also been confirmed in mammals to be a potential mechanism for paclitaxel-induced peripheral neuropathy 62,75." (PMID 35517405, 2022). "Since our research showed that increased MMP-13 activity in the epidermis promotes the development of paclitaxel-induced peripheral neuropathy, we further determined whether Mmp13 expression also changes in DRG neurons, which revealed no significant increase in these neurons." (PMID 36248261, 2022). "Thus, pharmacologic inhibition of MMP-13 may be a potential strategy to prevent paclitaxel-induced peripheral neuropathy 62,75." (PMID 35517405, 2022).
metabolic disorder (4 papers, 2020 to 2025). "In this study, Glycitin effectively reversed the TNF-α-mediated loss of Col-2 and Aggrecan, and reduced the level of MMP-13 and ADAMTS-5, suggesting that Glycitin is a key role in metabolic disorders of IVD." (PMID 38019477, 2023). "Positive staining for ACAN in the articular cartilage was significantly higher in C1 patients, while MMP13-positive cells dominated the collagen metabolic disorder C2 subtype." (PMID 33298863, 2020). "Then qPCR and Western blotting revealed that Se-Met supplementation reduced the production of ADAMTS-5 and MMP-13 and promoted the secretion of Aggrecan and Col-2 in response to mechanical overloading, while additional ML210 aggravated ECM metabolic disorder." (PMID 38252317, 2024). "Besides, the qPCR and Western blotting revealed that Se-Met supplementation reduced the production of ADAMTS-5 and MMP-13, and promoted the secretion of Aggrecan and Col-2, while knockdown of SelK aggravated ECM metabolic disorders." (PMID 38252317, 2024).
adenocarcinoma (3 papers, 2008 to 2015). A common cancer characterized by the presence of malignant glandular cells. "If our results show differences with the human adenocarcinomas regarding the expression MMP-2, -7 and -9, the overexpression of MMP-13 is consistent with human tumors." (PMID 26193700, 2015). "Here we confirmed those findings, and we observed a dramatic increase in Mmp3, Mmp10, and Mmp13 expression in CAC tissue relative to normal tissue; their expression was increased in dysplastic tissues and adenocarcinoma tissues and particularly in inflamed tissues." (PMID 25742789, 2015).
immune disorder (3 papers, 2013 to 2024). "In the present study, JQ1 also significantly inhibited Mmp13, Clec5a, and Gpr84 expression, and these inhibitory effects of JQ1 may play a potential role in immune disorder treatment, possibly through inhibition of macrophages and the ensuing inflammatory responses." (PMID 26582142, 2015).
genetic disease (2 papers, 2017 to 2025). "We propose that MMP9/MMP13 could be therapeutic targets for patients with this rare genetic disease." (PMID 28158191, 2017).
heart disease (1 paper, 2016). "Other studies have also demonstrated that exogenous H2S sources (NaHS) led to reduction of MMP-13 and/or MMP-8 levels in human chondrocytes under inflammatory conditions and in a model of rat heart disease." (PMID 27362269, 2016).
infectious disease (1 paper, 2024). A disorder directly resulting from the presence and activity of a microbial, viral, or parasitic agent in humans. "In fact, MMP13 is related to a specific inflammatory condition but also is reported as being involved in infectious diseases such as bovine respiratory infection." (PMID 39772115, 2024).
musculoskeletal disease (1 paper, 2024). "Some of the prominent MMPs involved in musculoskeletal disease are MMP-1, MMP-3, MMP-9, MMP-13, and MMP-14." (PMID 38790904, 2024).
MMP13 also shares sentences with these, for which no sentence is quoted: chronic periodontitis (12 papers); ductal carcinoma in situ (5); cardiovascular diseases (4); idiopathic pulmonary fibrosis (4); cholestasis (3); osteosclerosis (3); abdominal aortic aneurysm (2); anaplastic thyroid cancer (2); autoimmune disease (2); cholesteatoma (2); chronic obstructive pulmonary disease (2); colorectal (2); Coronary Artery Disease (2); Crohn disease (2); dermatitis (2); gingivitis (2); Hepatic steatosis (2); joint effusion (2); leukaemia (2); meningitis (2); metabolic syndrome (2); papillary thyroid carcinoma (2); psoriatic arthritis (2); rotator cuff tear (2); abdominal hernia (1); acute respiratory distress syndrome (1); adenocarcinoma in situ (1); amyloidosis (1); angiosarcoma (1); Anxiety (1).
A further 70 diseases each share a sentence with MMP13 in 1 paper.